IL6 (interleukin 6)
Diseases named in the same sentence as IL6 in open-access papers (continued):
Sharing a sentence is not in itself a finding about the gene and the disease.
atopic dermatitis (continued). "Clinical intake of DS has been reported to improve allergic skin responses by restoring mineral imbalances in atopic eczema/dermatitis syndrome, and by reducing levels of IgE and Th2 cytokines (IL4, IL6, and IL13) in allergic rhinitis." (PMID 38921545, 2024). "Atopic dermatitis is characterized by the excessive production of inflammatory cytokines, such as tumor necrosis factor-alpha (TNF-α) and IL-6, which are closely related to inflammation and pruritus." (PMID 39519379, 2024). "Among the isolated compounds, compounds 2–5, 7, 9, and 10 showed inhibitory effects on inflammatory cytokines (IL-1β, IL-6, and TNF-α) related to atopic dermatitis against TNF-α/IFN-γ-stimulated HaCaT keratinocytes at 10 μM." (PMID 39519643, 2024). "The results showed that CSSH reduced pro-inflammatory cytokines (IL-1β, IL-6, IL-8, MCP-1 and CXCL10) and atopic dermatitis-related cytokines (IL-4, CCL17, MDC and RANTES) in TNF-α/IFN-γ-induced HaCaT cells." (PMID 38931136, 2024). "According to previous studies, epithelial cells and keratinocytes damaged by atopic dermatitis produce proinflammatory cytokines (such as TNF-α, IL-1β, IL-6, and IL-8) and chemokines (such as CCL17/TARC, CCL22/MDC)." (PMID 36793948, 2023). "IL-6, S100A8, and S100A9 are three key regulators that display a positive biological relationship with atopic dermatitis and serve as major inflammatory markers under PM exposure." (PMID 35697899, 2022). "In atopic dermatitis, damaged epithelial cells and keratinocytes produce proinflammatory cytokines and chemokines such as TNF-α, IL-1β, IL-6, IL-8, CCL17, and CCL22." (PMID 36158872, 2022). "Angelicae Gigantis Radix attenuated scratching behavior, and 2,4-dinitrochlorobenzene-induced atopic dermatitis-like skin lesions by reducing serum IgE, histamine, TNF-α, IL-6, and COX-2 expression in skin tissue from mouse models." (PMID 35215322, 2022). "Patients with atopic dermatitis seem to have a higher expression of TGF-β and other inflammatory cytokines like IL-6, IL-8 and IL-10 compared to healthy individuals." (PMID 34012511, 2021). "At the onset of atopic dermatitis, skin inflammation occurs and the expression levels of inflammatory markers, such as TNF-α, IL-6, iNOS, and COX-2, increase." (PMID 32545274, 2020). "OIR3 was able to reduce oxazolone-induced skin inflammation in allergic dermatitis mouse model via the inhibition of TNF-α, IL-1β and IL-6 mRNA expression." (PMID 31775224, 2019). "Importantly, in an atopic dermatitis-like cell model induced by TNFα/IFNγ, LF216EV significantly modulated the expression of immune regulatory genes (TSLP, TNFα, IL-6, IL-1β, and MDC), indicating its potential functionality in atopic dermatitis." (PMID 40028723, 2025). "(2014) reported a significant increase in IL‐4 concentrations in dogs with atopic dermatitis, while no change in IL‐6 and IL‐10." (PMID 38648253, 2024). "Our findings are in line with other preclinical studies beyond atopic dermatitis wherein HSP90 inhibition exerted anti-inflammatory effects by targeting several inflammatory cytokines (e.g. TNF, IL-1β, and IL-6) and signalling pathways (e.g. ERK1/2, p38, and JNKs)." (PMID 38274815, 2023). "Astragalin is associated with various pharmacological and biological activities, including anti-inflammatory, antioxidant activity, anti-atopic dermatitis activity, TNF-a, IL-1b, and IL-6 production inhibiting activity, and inhibiting histamine release in human blood cells." (PMID 33968110, 2021). "Recently, Kim demonstrated the effects of Costaria costata extract on atopic dermatitis via suppressing expression of TARC, eotaxin, TNF-α, and IL-6 in TNF-α and IFN-γ-stimulated HaCaT keratinocytes as well as release histamine in PMA and A23187-stimulated MC/9 mast cells." (PMID 30642008, 2019).
atopic dermatitis (continued). "Both IL-6 and IFN-γ are related to PE development via their effects on endothelial cells and inflammation, and both of these cytokines were important for microvascular angiogenesis and leakage in an atopic dermatitis mouse model." (PMID 22054060, 2011). "For example, increased levels of interleukin (IL)-6 andtumor necrosis factor (TNF)-α, which exacerbate immune systemhyperactivity and compromise skin barrier function, often result in chronicinflammation observed in conditions such as urticaria and atopic dermatitis." (PMID 41209500, 2025). "The immunomodulatory effects of probiotics can reduce the severity of atopic dermatitis by inhibiting Th2 cell responses, cytokines such as IL-4, IL-5, IL-6, and IL-13 are no longer secreted, INF-γ (cytokines released by Th1 cells) is decreased, phagocytosis is stimulated, and serum IgA increases." (PMID 39781533, 2025). "In addition, it is necessary to determine whether IL6, CXCL8, and CCL2 levels are upregulated in dogs with atopic dermatitis and whether the symptoms of atopic dermatitis are alleviated when these cytokines are controlled." (PMID 39852930, 2025). "It is important to highlight that classical inflammatory markers such as TNF-α, IL-6, etc., may not consistently serve as indicators for atopic dermatitis induced by DNCB." (PMID 38834629, 2024). "Sleep disturbances in atopic dermatitis are not only due to sleep deprivation related to nighttime itching but also to dysregulation in the release of inflammatory mediators (IL-1b, IL-2, TNF-a, IFN-g, IL-6, IL-4, and IL-10) and neuroendocrine molecules such as cortisol and melatonin." (PMID 38731996, 2024). "Notably, astersaponin J exhibited a dose-dependent reduction in IL-1β, IL-6, and TNF-α levels, suggesting that it could be a potential candidate of a therapeutic agent for atopic dermatitis." (PMID 39519643, 2024). "Furthermore, in a model of 2,4-dinitrochlorobenzene (DNCB)-induced atopic dermatitis in mice, topical application of verbascoside reduced scratching and skin lesion severity, lowered IgE and IL-4 and IL-13 levels, and decreased inflammatory cytokines (TNF-α, IL-6, IL-4) in affected skin." (PMID 40724000, 2025). "However, it is crucial to emphasize that no significant changes were observed in classic factors of atopic dermatitis, such as TSLP and pro-inflammatory cytokines (TNF-α, COX-2, IL-6, IL-31, etc.), in our study." (PMID 38834629, 2024).
Hypoalbuminemia (122 papers, 2012 to 2026). The concentration of albumin in the blood circulation is below the lower limit of normal. "A further immunological cascade boosts IL-6 and IL-1β levels, causing increased blood vessel permeability, leading to transcapillary albumin loss and hypoalbuminemia." (PMID 41008744, 2025). "Patients with malignant tumors often experience hypoalbuminemia caused by the release of a large number of cytokines, including IL-6 released by tumor cells, which can inhibit the synthesis and secretion of albumin by liver cells." (PMID 36313734, 2022). "Hypoalbuminemia, inflammatory status (C-reactive protein >10 mg/dL or interleukin-6 ≥10 pg/mL), and female gender were associated with increased, while age ≥85 years with decreased risk of seropositivity." (PMID 36361095, 2022). "Serum interleukin-6 is also increased in acute and chronic inflammatory situations and has been shown to be associated with hypoalbuminemia." (PMID 33215031, 2020). "The etiologies of hypoalbuminemia include malnourishment, hepatic impairment, decreased hepatic synthesis of albumin due to interleukin (IL)-1, IL-6, and tumor necrosis factor (TNF)-α, and protein loss via the kidney or gastrointestinal tract." (PMID 31731708, 2019). "We evaluated the association between markers of inflammation (IL-6, hsCRP, hypoalbuminemia and albuminuria) and ssEFV in this pre-dialysis CKD cohort." (PMID 23351146, 2013). "In addition, recent studies have shown that increased inflammatory markers and interleukin-6 concentrations in serum and ascites appear to be associated with severe hypoalbuminemia." (PMID 39039452, 2024). "Sustained release of inflammatory cytokines such as interleukin-6 or tumor necrosis factor-α may cause muscle and fat mass wasting and hypoalbuminemia in patients with metabolic disturbances." (PMID 38398372, 2024). "We speculate that cytokine production (i.e., IL-6) by EOC cells causes both hypoalbuminemia and decreased ALC, leading to decreased PNI." (PMID 31217896, 2019). "Phase angle and s-albumin, together with additional biochemical nutritional and inflammatory parameters (i.e., s-CRP, IL-6), may help to monitor and adjust dry body weight in wasted HD patients, since hypoalbuminemia is also caused by hemodilution during states of chronic volume expansion." (PMID 35458220, 2022). "Within this state, IL-6 suppresses hepatic albumin synthesis while promoting acute-phase protein production, and increased vascular permeability exacerbates hypoalbuminemia." (PMID 41601745, 2026). "The ascites and hypoalbuminemia observed among patients with higher IL-6 likely reflect the effect of IL-6 on the liver, promoting acute phase reactants while decreasing albumin production." (PMID 40646134, 2025). "Pro-inflammatory cytokines like IL-6 promote the production of acute-phase proteins while suppressing albumin synthesis, leading to hypoalbuminemia." (PMID 41012833, 2025). "Hypoalbuminemia, commonly seen in cancer patients, results from cytokine-mediated catabolism (e.g., IL-6, TNF-α), reduced protein synthesis, and increased vascular permeability." (PMID 41156248, 2025). "On univariate Cox proportional hazards analysis elevated IL-6, hypoalbuminemia, and a high Wang prognostic score were significantly associated with worse OS." (PMID 40646134, 2025). "Research has demonstrated that elevated levels of UA can stimulate the release of inflammatory cytokines such as interleukin-6 and tumor necrosis factor-alpha, which in turn inhibit albumin synthesis, leading to hypoalbuminemia." (PMID 39659906, 2024). "In cancer patients, tumor-related cytokines like tumor necrosis factor-α and interleukin-6 can hinder albumin gene transcription in liver cells, leading to hypoalbuminemia." (PMID 39767217, 2024). "The blood tests revealed elevated C-reactive protein levels, immunoglobulin G, IL-6, and hypoalbuminemia in all patients, and the immunoelectrophoretic analysis confirmed polyclonal hypergammaglobulinemia." (PMID 37102781, 2023).
Hypoalbuminemia (continued). "Hypoalbuminemia enhances the secretion of various inflammatory factors, such as interleukin-6 (IL-6) and tumor necrosis factor alpha (TNF-α), which further stimulates tumor inflammation progression." (PMID 37853186, 2023). "Elevated IL-6 levels can impair the liver’s ability to synthesize albumin, leading to hypoalbuminemia." (PMID 37512137, 2023). "The risk increased with hypoalbuminemia, higher serum CRP level (as well as CPR > 3 mg/dL) or plasma IL-6 level (as well as IL-6 ≥ 10 pg/mL), inflammatory status (CRP > 10 mg/dL or IL-6 ≥ 10 pg/mL), and female gender." (PMID 36361095, 2022). "There is a large body of evidence that states that oral supplementation decreases hospital admission rates, serum IL-6 levels, improves hypoalbuminemia, physical functionality, PEW, better body composition markers, quality of life, and reduces mortality." (PMID 35938133, 2022). "Albumin is widely recognized as an indicator of nutritional levels, and the mechanism of hypoalbuminemia is related to the increase in two inflammatory cytokines, tumor necrosis factor-α and interleukin-6, which inhibit the synthesis of albumin." (PMID 36386541, 2022). "The inflammatory state and, particularly, high interleukin-6 and tumor necrosis factor (TNF)-alpha concentrations are the two main markers associated with hypoalbuminemia." (PMID 35010957, 2021). "HHV8-positive MCD shows systemic symptoms, multiple lymphadenopathy, cytopenia, splenomegaly, hypoalbuminemia, hypergammaglobulinemia, elevated serum levels of inflammatory markers such as C-reactive protein and interleukin 6 (IL-6)." (PMID 33906629, 2021). "Few studies have shown that hypoalbuminemia strongly associates with increased CRP and/or IL-6 levels in CKD patients, while data on the association of BMI with inflammation within these clinical settings is still contradictory." (PMID 31316299, 2019). "Measurable parameters in the blood suggest a systemic inflammatory response including: elevated CRP, IL-6 and other pro-inflammatory cytokines, hypoalbuminaemia, leucocytosis and neutrophilia." (PMID 28384249, 2017). "Proinflammatory cytokines, such as interleukin-6 (IL-6) and tumor necrosis factor (TNF), are elevated and are associated with hypoalbuminemia, left ventricular diastolic dysfunction, and mortality in PD patients." (PMID 25286027, 2014). "IL-6 offers prognostic insight beyond hypoalbuminemia and the Wang score." (PMID 40646134, 2025). "Cancer-associated inflammation reduces hepatic Alb synthesis via cytokines such as interleukin-6, and persistent hypoalbuminemia may contribute to cancer progression and mortality." (PMID 41340164, 2025). "Indeed, hypoalbuminemia correlates with increased levels of multiple inflammatory factors, such as interleukin-6 (IL-6) and tumor necrosis factor alpha (TNF-α), leading to tumor inflammation progression." (PMID 40216704, 2025). "We also skipped assessing inflammation indicators like C-reactive protein or interleukin-6, which could clarify ties among hypoalbuminemia, albuminuria, and CVDs." (PMID 41536368, 2025). "This adds focus to the higher peak and persistence of pro-inflammatory cytokines IL-6 and TNFα, hyperlactatemia, hypoalbuminemia, and corticosterone, as key mechanisms underlying non-survivorship after high-grade CLP." (PMID 41155249, 2025). "In addition to the impact on the metabolism, hypoalbuminemia also affects the immunity, such as inducing the cytokines of tumor necrosis factor-a, interleukin-6, and interleukin-1, which promotes the cancer progression." (PMID 39064013, 2024). "Additionally, high interleukin-6 levels produced by cancer cells inhibit the synthesis of albumin, resulting in hypoalbuminemia." (PMID 38791922, 2024). "With elevated IL-6 levels, patients develop hypoalbuminemia." (PMID 37234775, 2023). "With the activation of inflammatory cytokines, such as IL-6 or TNF-α, loss of appetite with subsequent muscle wasting and hypoalbuminemia may be seen." (PMID 35740095, 2022).
Hypoalbuminemia (continued). "However, both low ALC and hypoalbuminemia have been reported to be associated with shorter survival in patients with EOC, which frequently expresses IL-6." (PMID 31217896, 2019). "Hypoalbuminemia may also reflect the inflammatory activity induced by cytokines such as interleukin-6 (IL-6) or tumor necrosis factor." (PMID 31217896, 2019). "In dogs, cytokine IL6 suppresses albumin synthesis and may be released by neoplastic cells, and this might contribute to the progressive hypoalbuminaemia observed in AL." (PMID 30305106, 2018). "KD patients often exhibit varying degrees of hypoalbuminemia, which may be related to various inflammatory cytokines present, such as vascular endothelial growth factor, tumor necrosis factor-α, interleukin-1, and interleukin-6." (PMID 40574952, 2025). "Suppressed albumin synthesis is partly due to the activation of cytokines such as IL-1, IL-6, and TNF-α, a common observation in cancer, resulting in hypoalbuminemia." (PMID 37492594, 2023). "The hypoalbuminemia seen in the 2% casein diet group can be attributed to significant increases in the levels of the acute-phase proteins TNF-α, IL-1, IL-6, and CRP compared with the controls." (PMID 32518615, 2020). "Hotelling's t analysis revealed significant differences among the presurgical albumin infusion (B), presurgical normal protein diet (C), and hypoalbuminemia (D and E) diet groups in terms of serum levels of albumin, TNF-α, IL-1, IL-6, CRP, and MMP-8 (P=0.01)." (PMID 32518615, 2020). "Albumin is a negative acute phase protein; therefore, release of proinflammatory cytokines (eg, IL‐6, TNF) leads to reduced albumin synthesis in the liver and to hypoalbuminemia in cancer patients." (PMID 35847697, 2020). "The results of our meta-analysis are in accordance with these reports, in which n-3 PUFAs reduced host inflammatory response by decreasing the concentration of IL-6, TNF-α, and CRP, and improving hypoalbuminemia." (PMID 28410575, 2017). "In digestive tumors common biochemical parameters used were: albumin (alone or hypoalbuminemia), carcinoembryonic antigen (CEA), cancer antigen 19–9 (CA19-9) and interleukins (IL-6, IL-8, IL-2)." (PMID 26717416, 2015). "Biochemical parameters used with CRP (specifically in renal cell carcinoma) were: albumin (alone or as hypoalbuminemia), LDH, and interleukins (IL-6, IL-8, IL-2)." (PMID 26717416, 2015). "IMID exposure resulted in significant hepatocellular and neuronal damage characterized by elevated serum ALT and AST, hypoalbuminemia, hypoproteinemia, increased MDA, suppression of SOD and CAT activities, and upregulated mRNA expression of TNF-α, IL-6, and HMGB1." (PMID 41838129, 2026). "In the state of hypoalbuminemia, the human body is more prone to trigger systemic inflammatory responses and immune suppression,resulting in elevated levels of C-reactive protein (CRP) and interleukin-6 (IL-6) in the body." (PMID 40641962, 2025). "After abdominal infection, the absorption of endotoxin increases, thus stimulating the production of inflammatory mediators such as TNF, IL-1, and IL-6 in liver macrophages and inhibiting the translation of the ALB transcript, ultimately leading to hypoalbuminemia." (PMID 38166815, 2024). "Hypoalbuminemia also leads to hepatotoxicity among TB patients due to triggering inflammatory responses such as tumor necrosis factor (TNF) and interleukin (IL)-6 in TB patients, which leads to increased vascular permeability, increasing degradation, and decreasing synthesis of albumin." (PMID 39502524, 2024). "Hypoalbuminemia is a feature of inflammation as confirmed in our study by the inverse relation between albumin and CRP or IL-6, but it might also the consequence of a high clearance of oxidized form of albumin." (PMID 34299080, 2021). "Similarly, majority had hypoalbuminemia (95.4%), raised lactate dehydrogenase (LDH) (93.6%), C-reactive protein (CRP) (98.8%), D-dimer (98.3%), serum ferritin (92.4%) and interleukin 6 level (95.4%)." (PMID 34548976, 2021).
Hypoalbuminemia (continued). "However, after pre- and postsurgical albumin infusion or administration of a normal protein diet, the levels of TNF-α, IL-1, IL-6, CRP, and MMP-8 were significantly reduced relative to the hypoalbuminemia group." (PMID 32518615, 2020). "The result of hypoalbuminemia in patients with cancer might be due to cancer patient, pro-inflammatory cytokines (TNF-α, IL-2, and IL-6) induced positive acute phase reactant synthesis compete for nutrient in liver leads to decreases in serum albumin production." (PMID 36869395, 2023). "Since the inflammatory cytokines TNF-α, IL-1, IL-6, and IL-8 play an essential role in the pathogenesis of AAV and negatively impact Alb levels, it could be suggested that hypoalbuminemia present in patients with AAV are proportional to the degree of inflammation." (PMID 35797397, 2022). "IL-1, IL-6 and TNF-α, which are highly expressed in the serum of patients with hepatic alveolar echinococcosis, can inhibit the synthesis of ALB, which also leads to hypoalbuminemia; On the other hand, lymphocytes play an important role in immune monitoring and immune mediation." (PMID 34248983, 2021).